HIF1A (hypoxia inducible factor 1 subunit alpha)
Diseases named in the same sentence as HIF1A in open-access papers (continued):
Sharing a sentence is not in itself a finding about the gene and the disease.
ovarian carcinoma (continued). "Moreover, we observed that HIF-1α, located downstream of the mTOR, is implicated in LPA-induced DDR2 expression and ovarian cancer cell invasion." (PMID 34065317, 2021). "Additionally, β-escin was found to decrease the stemness of ovarian cancer cells, inhibit extracellular matrix production in the tumor microenvironment, and inhibit HIF1α stability in ovarian cancer cells and the tumor microenvironment." (PMID 34439084, 2021). "The transcription factor HIF-1α regulates more than 100 genes involved in cancer cell proliferation, apoptosis and angiogenesis, and plays a key role in hypoxia-induced chemoresistance in ovarian cancers." (PMID 33802884, 2021). "Ginsenoside Rg3 could down-regulate DNA methyltransferase DNMT3A and decrease the methylation in the promoter region of miR-519a-5p precursor gene, thus upregulating miR-519a-5p to inhibit the HIF-1α-stimulated Warburg effect in ovarian cancer." (PMID 34950039, 2021). "In epithelial ovarian cancer cells, HIF1α and HIF2α are reciprocally regulated by DNM2." (PMID 33240194, 2020). "Furthermore, in vitro study revealed that miRNA transfection of mimic-155-5p that conjugated with chitosan nanoparticle can induce inhibition of viability of ovarian cancer cell line SKOV3 by decreasing HIF1α." (PMID 33062603, 2020). "Evidence suggests that NEK6 is a downstream target of HIF-1α in ovarian cancer." (PMID 32294979, 2020). "Hypoxia-inducible factor 1-alpha (HIF-1α), a master regulator of hypoxic response, is upregulated in ovarian tumour tissues and is correlated with chemo-resistance and decreased overall survival for ovarian cancer patients." (PMID 33143089, 2020). "The anti-angiogenic effect of gallic acid in ovarian cancer is due to the downregulation of the Phosphatase and tensin homologue deleted on chromosome 10/Protein kinase B/Hypoxia-inducible factor-1alpha (PTEN/AKT/HIF-1α) pathway and inhibition of vascular endothelial growth factor (VEGF) expression." (PMID 33173425, 2020). "Moreover, in the present study, the expression of HIF-1α was gradually increased in hypoxic ovarian cancer cells when exposed to prolonged hypoxia." (PMID 32312328, 2020). "Hence, HIF-1α is a factor downstream of FSH, and FSH also stimulates HIF-1α transcription and translation in ovarian cancer cells." (PMID 33114509, 2020). "Association analysis between HIF-1α, MDR1 and LAPTM4B expression in ovarian cancer blood specimens." (PMID 30746305, 2019). "The up-regulated HIF1α promoted the glucose uptake and lactate generation of ovarian cancer cells." (PMID 30988076, 2019). "The purpose of this study was to investigate whether pharmacokinetic dynamic contrast-enhanced (DCE) perfusion parameters are associated with a specific marker of hypoxia, hypoxia-inducible factor 1 alpha (HIF-1α) in ovarian cancer (OC)." (PMID 31437208, 2019). "Interestingly, overexpression of miR-199a and miR-125b in ovarian cancer cells decreased the expression of the hypoxia-inducible factor 1-alpha (HIF-1α) and vascular endothelial growth factor, which suppressed tumor-induced angiogenesis." (PMID 31717786, 2019). "Inhibition of HIF-α expression delayed the progression of certain types of cancers such as colon cancer and ovarian cancer, indicating that the inhibition of HIF-1α expression may serve as a potential therapeutic target for different types of malignancies." (PMID 29899167, 2018). "For instance, it has been demonstrated that the endothelin-1/ endothelin A receptor (ET-1/ETAR) axis in epithelial ovarian cancer (EOC) cells induces vascular-endothelial growth factor (VEGF) expression through HIF-1α nuclear accumulation, resulting in the invasion of cancer cells." (PMID 29482638, 2018). "The results show that hypoxia can promote the proliferation of ovarian cancer cells by affecting the invasion and adhesion functions through the dysregulation of ErbB signaling, which may be governed by the HIF-1α-TGFA-EGFR-ErbB2-MYC axis." (PMID 29482638, 2018).
ovarian carcinoma (continued). "Our study demonstrated that c-Src contributed to hypoxic microenvironment-rendered paclitaxel resistance in human epithelial ovarian cancer cells by G2/M phase arrest deterioration, and through c-Src suppression, FV-429 was capable of reversing the resistance by blocking c-Src/Stat3/HIF-1α pathway." (PMID 29324735, 2018). "Therefore, we are intended to explore the relationship between AEG‐1 and HIF‐1α involved in metastasis of ovarian cancer in the current study." (PMID 28401704, 2017). "And strongly staining for HIF-1α has been found in ovarian cancer patients with poor survival." (PMID 28878214, 2017). "Moreover, SIRT1 was found to be the downstream target gene of HIF-1α, which was involved in the promotion of cancer stem cells-like features in ovarian cancer cells by hypoxia, and NF-κB signaling pathway was involved in hypoxia-induced SIRT1 up-regulation." (PMID 28878214, 2017). "The results of this study indicated that in ovarian cancer HIF1α and SIRT1 might serve as potential therapeutic targets." (PMID 28878214, 2017). "Additionally, HIF-1α expression was at a high level in tumor from hypoxia-pretreatment ovarian cancer cells." (PMID 28878214, 2017). "Moreover, Sirtuin type 1 (SIRT1) was found to be the downstream target gene of HIF-1α, which was involved in the promotion of CSCs-like features in ovarian cancer cells induced by hypoxia." (PMID 28878214, 2017). "Moreover, exposure of ovarian cancer cells to hypoxia was found to reduce the methylation level of S100A4 first intron that was shown to bind to HIF-1α, thereby enhancing ovarian cancer cell invasiveness and its metastasis potential." (PMID 29069865, 2017). "To establish such a role for HIF1α in LPA-induced EMT in ovarian cancer cells, we tested whether the silencing of HIF1α attenuates the expression of EMT markers in these cells." (PMID 27166196, 2016). "A previous report has demonstrated that exogenous LPA stimulation synergistically enhanced hypoxia-induced stabilization of HIF1α and hypoxia, which in turn, could enhance the oncogenic responsiveness of ovarian cancer cells to LPA." (PMID 27166196, 2016). "Taken together with the observation that LPA stimulates HIF1α, it can be surmised that the activation of HIF1α by LPA could promote EMT in ovarian cancer cells." (PMID 27166196, 2016). "Finally, we demonstrate that the inhibition of this pathway using PX-478, a HIF1α inhibitor, drastically decreases the migration of ovarian cancer cells." (PMID 27166196, 2016). "Overexpression of constitutively active Gαi2, without any exogenous LPA, resulted in an increase in HIF1α levels, suggesting that Gαi2-signaling is sufficient and responsible for mediating the effect of LPA in increasing the levels of HIF1α levels in ovarian cancer cells." (PMID 27166196, 2016). "Furthermore, earlier findings suggested that a thiol-sensitive mechanism contributes to the As(III)-induced VEGF and HIF-1α expression in human ovarian cancer cells." (PMID 27286880, 2016). "It has been shown that miR-138 may have an effect on tumor metastasis by targeting SOX4 and HIF1a in ovarian cancer and targeting MMP2/MMP9 in cholangiocarcinoma." (PMID 25845814, 2015). "The results may have important implications for the potential use of SENP1 regulation in HIF-1α inhibition and for improving chemosensitivity of ovarian cancer cells to cisplatin." (PMID 26548925, 2015). "Pancreatic and ovarian cancers have high expression of HIF-1α." (PMID 25888489, 2015). "Nobiletin had a certain impact on HIF-1α expression of ovarian cancer cells." (PMID 25845666, 2015). "Hypoxia-inducible factor 1 alpha (HIF-1α) is closely related to chemoresistance of ovarian cancers." (PMID 26548925, 2015). "The results showed SDHB affected ovarian cancer progression by altering HIF-1α expression." (PMID 25491408, 2014). "The expression of HIF-1α was strongly elevated in SDHB-silenced ovarian cancer cells." (PMID 25491408, 2014).
ovarian carcinoma (continued). "HIF-1α is the key cellular survival protein in hypoxic ovarian cancer." (PMID 23946798, 2013). "In order to identify the expression levels of several cancer-related genes in the pathogenesis of primary ovarian cancer, the present study examined the mRNA levels of hMOF, CA9, VEGF, HIF1α and hSTC1 in 47 patients with pathologically-diagnosed ovarian cancer using PCR." (PMID 24137335, 2013). "The present study evaluated the expression of HIF-1α and Twist2 and further investigated whether Twist2 is involved in hypoxia-induced apoptosis in ovarian cancer." (PMID 23946798, 2013). "miR-21 may be involved in the development of drug resistance and the regulation of MDR1/P-gp expression, at least in part, by targeting HIF-1α in ovarian cancer cells." (PMID 24137413, 2013). "HIF-1α is also highly expressed in female-specific cancers such as ovarian cancer." (PMID 23819061, 2013). "The data indicate that LOX and HIF-1α expression is related to ovarian cancer malignancy." (PMID 23545606, 2013). "We hypothesized that hypoxia-induced LOX upregulates the expression of HIF-1α which promotes ovarian cancer cell invasion and metastasis." (PMID 23545606, 2013). "Previous studies indicated that miR-138 may have an effect on tumor metastasis by targeting SOX4 and Hif1a in ovarian cancer, MMP2/MMP9 in cholangiocarcinoma cells and FAK in hela cells." (PMID 24171926, 2013). "However, we were unable to confirm the direct interaction between miR-199a and HIF-1α in ovarian cancer cells, suggesting an indirect effect of miR-199a on HIF-1α expression." (PMID 23437196, 2013). "In conclusion, the present study demonstrated that miR-21 may regulate the expression of MDR1/P-gp, at least in part, by targeting HIF-1α, which is involved in the development of drug resistance in paclitaxel-resistant ovarian cancer A2780/taxol cell lines." (PMID 24137413, 2013). "Therefore baicalein is more effective in inhibiting cancer cell viability and expression of VEGF, HIF-1α, cMyc, and NFκB in both ovarian cancer cell lines." (PMID 23502466, 2013). "Additionally, LOX is expressed intracellularily within ovarian cancer cells and facilitates cell migration through the regulation of HIF-1α." (PMID 23545606, 2013). "Hypoxia-inducible factor-1 α (HIF-1α) is an important prognostic factor in ovarian carcinoma." (PMID 23946798, 2013). "HIF-1α is an independent adverse prognostic factor in ovarian cancer." (PMID 23946798, 2013). "Therefore, additional therapeutic approaches targeting HIF-1α or platelet aggregation may have the potential to improve the prognosis of patients with ovarian carcinoma." (PMID 39941717, 2025). "Besides angiogenesis, HIF-1α is crucial for the metabolic reprogramming of ovarian cancer cells." (PMID 40136686, 2025). "ecDNA-mediated amplification of the HIF1A gene in the SKOV3-cisR cell line has been previously linked to platinum resistance by inducing miR-223 secretion from macrophages and their derived exosomes, thereby promoting therapy resistance in ovarian cancer patients." (PMID 40428339, 2025). "Consequently, targeting the NEK6/HIF-1α axis may represent a novel therapeutic strategy to improve treatment outcomes in patients with treatment-resistant ovarian cancer." (PMID 41154634, 2025). "Whilst the use of aspirin may demonstrate benefits for solid tumors or for those with hereditary cancer predisposition (i.e., Lynch syndrome), its efficacious role in ovarian cancer requires further exploration alongside targeted agents aimed at HIF-1α or improving tissue oxygenation." (PMID 38539519, 2024). "Consistent with our research, a previous study on ovarian cancer indicated that extracellular LPA could reprogram cancer cell metabolism via an HIF1A-mediated pseudo-hypoxic response, indicating that HIF1A regulation by LPA might be a common mechanism in tumorigenesis." (PMID 37990271, 2023). "This suggests that TGF-β may regulate DIMP through LCN2, HMOX1, or HIF1A in ovarian cancer." (PMID 38186569, 2023).
ovarian carcinoma (continued). "CD39+ CD73+ MDSCs have also been traced in ovarian cancer, where metformin treatment on MDSCs purified from peripheral blood of ovarian cancer patients or healthy donors showed promising results in restoring anti-tumor T-cell immunity by inhibiting HIF1α pathway." (PMID 37895302, 2023). "Therefore, we first investigated whether NOX4 was regulated by HIF-1α in A2780 ovarian cancer cells." (PMID 34209278, 2021). "Therefore, we assume that HVEM might lead to the development of ovarian cancer by regulating the expression of HIF-1α." (PMID 32312328, 2020). "Therefore, we speculated that HVEM might exert its effects in the development of ovarian cancer via regulation of HIF-1α expression." (PMID 32312328, 2020). "Moreover, over-expression of HIF-1α or AKT inhibited acacetin-restraining VEGF protein level, demonstrating that AKT and HIF-1α could be the downstream key factors in suppressing VEGF expression in ovarian cancer cell." (PMID 32009958, 2019). "Therefore, the HCG/LHR axis induces VM by HIF-1α regulation in ovarian cancer." (PMID 31612116, 2019). "This work evaluated AEG-1, HIF-1α, NF-κB, and VEGF protein and mRNA amounts in epithelial ovarian cancer (EOC) cells cultured under hypoxic conditions and found potential associations of AEG-1, NF-κB, and VEGF expression levels with hypoxia induced ovarian cancer growth." (PMID 29770329, 2018). "Therefore, HIF‐1α is a critical regulator of ETS‐1 expression under LPA exposure in ovarian cancer." (PMID 28236660, 2017). "Therefore, we tested whether LPA-stimulated invasive migration of ovarian cancer cells could be attenuated by the inhibition of HIF1α by PX-478." (PMID 27166196, 2016). "Therefore, ROS itself and the HIF-1α signaling pathways may present potential targets to be exploited therapeutically in patients with metastatic and recurrent ovarian cancers." (PMID 25174950, 2014). "The identification of potential targets such as HIF1A and KRT80 holds promise for the development of innovative therapeutic strategies against drug-resistant ovarian cancer." (PMID 40428339, 2025). "Collectively, regulation of SHMT2 isoform expression via alternative promoter usage by transcription factors HIF1α and TFE3 provides a novel basis and potential drug targets for the clinical treatment of platin-resistant ovarian cancer." (PMID 40097394, 2025). "In the investigation of epithelial ovarian cancer (EOC), there is evidence demonstrating that ADM functions as an upstream regulatory molecule of VEGF and HIF-1α, thereby facilitating tumor angiogenesis through the upregulation of VEGF and HIF-1α expression." (PMID 40565016, 2025). "In ovarian cancer cells, there exists a negative regulatory relationship between AMPK phosphorylation and HIF-1α protein." (PMID 40191206, 2025). "The Subsequently, we investigated how the silencing of TRPM7 affected AMPK activation, the expression of HIF-1α, OXPHOS, and glycolysis in ovarian cancer cells." (PMID 40813985, 2025). "In ovarian cancer, H2O2 is also essential in the EGF-induced PI3K/AKT/p70S6K1 pathway activation, which induces VEGF mRNA expression through HIF-1α activation." (PMID 40847302, 2025). "This article summarizes available information on the effects of pentacyclic triterpenoids on the PI3K/AKT/mTOR, MAPK/ERK, NF-κB, JAK/STAT, Notch, HIF-1α, TGF-β, Wnt/β-catenin, Hippo, and Hedgehog signaling pathways in ovarian cancer cells." (PMID 41373772, 2025). "Ursolic acid was reported to significantly decrease HIF-1α and adenosine triphosphate (ATP)-binding cassette efflux transporter G2 (ABCG2) expression in SK-OV-3 ovarian cancer cells under hypoxic conditions." (PMID 41373772, 2025). "Regarding therapy resistance, FABP4 enhances mitochondrial β-oxidation to reduce apoptosis in ovarian cancer, and FABP5 promotes chemoresistance in HCC via the HIF-1α pathway." (PMID 40717587, 2025).
ovarian carcinoma (continued). "IL-6 additionally induces nuclear translocation and transcriptional activation of HIF-1α via STAT3, enhancing cisplatin resistance in ovarian cancer cells." (PMID 41383608, 2025). "In drug-resistant ovarian cancer cells, it was observed that CRABP2 increases HIF1α expression levels and enhances its nuclear localization." (PMID 40657374, 2025). "In conclusion, we suggest that the mechanism behind GP‐2250's anti‐neoplastic effect on ovarian cancer cells includes inhibition of glycolysis via modulation of HK2 activation and expression and inhibition of HIF‐1α induced VEGF secretion." (PMID 39114948, 2024). "Second, ETAR activation couples the scaffold protein β-arrestin to HIF-1α, which was critical for transcription of HIF-1α target genes in ovarian cancer cells." (PMID 38785410, 2024). "By downregulating AKT, HIF-1α secretion is inhibited, leading to the suppression of VEGF in ovarian cancer cells." (PMID 38611849, 2024). "One important finding of our research is that CRABP2 can affect the expression and subcellular localization of HIF1α, and the effect of CRABP2 on drug sensitivity of ovarian cancer is dependent on HIF1α." (PMID 38195606, 2024). "For example, a recent study demonstrated that HIF-1α is transported to the nucleus where it dimerizes with HIF-1β, resulting in promotion of cell migration, proliferation, invasion and tumor growth in ovarian cancer." (PMID 38806469, 2024). "Both HIF1A and TWIST1 are integral to the PI3K pathway, which was described to be crucially involved in the tumorigenesis of ovarian cancer." (PMID 37370765, 2023). "Previous research found that MCP-1 can facilitate tumor cell migration and omental metastasis of ovarian cancers via the PI3K/AKT/mTOR pathway and downstream HIF-1α and VEGF-A." (PMID 37298699, 2023). "The signaling mediators of glucose metabolism in ovarian cancer include PI3K/Akt, PTEN, MYC, and HIF1α." (PMID 37277821, 2023). "IL-6 was reported to promote transcription of HIF1A by activating STAT3 signaling, and enhancing cisplatin resistance of ovarian cancer cells both in vitro and vivo by upregulation of HIF1A." (PMID 36761955, 2023). "AM expression positively correlated with HIF-1α, VEGF, or microvessel density in epithelial ovarian cancer." (PMID 36980580, 2023). "In contrast, the expression of HIF1A and HMOX2 involved in iron regulation was found to be higher in ovarian cancer tissues." (PMID 38186569, 2023). "Salt-inducible kinase 2 (SIK2) overexpression in ovarian cancer cells activates the PI3K/AKT/HIF-1α pathway, upregulates HIF-1α expression, directly upregulates the transcription of major glycolytic genes and promotes glycolysis." (PMID 36311734, 2022). "In ovarian cancer, mTORC1 regulates glucose metabolism during CD8+ Treg differentiation by modulating HIF1α expression." (PMID 36311734, 2022). "In ovarian cancer cells, CX3CR1 was upregulated in a course of hypoxia-mediated regulation of hypoxia-inducible factor-1α (HIF-1α)." (PMID 36246557, 2022). "A previous study found that the Rho/ROCK pathway is essential to HIF-1α expression in ovarian cancer cell lines and is an upstream regulator of HIF-1α accumulation in ovarian cancer." (PMID 35997665, 2022). "Hypoxia induced HIF-1α protein expression in ovarian cancer cells, which was very weak in the TRPM7 silencing ovarian cancer cells." (PMID 35101076, 2022). "In support of this finding, it was observed that CCL2 facilitates migration and metastasis in ovarian cancer by activating the PI3K–AKT–mTOR pathway and its downstream effectors, HIF-1α and VEGF-A." (PMID 35884700, 2022). "In accordance with our results, CoCl2 treatment (a hypoxia mimetic) activated NF-κB and induced HIF-1α protein expression in both A2780 and SKOV3 ovarian cancer cells." (PMID 35464826, 2022). "Our data revealed that TRPM7 silencing down-regulated HIF-1α expression, but enhanced AMPK activation in ovarian cancer cells, extending previous observations." (PMID 35101076, 2022).